USP18 (ubiquitin specific peptidase 18)
Diseases named in the same sentence as USP18 in open-access papers (continued):
Sharing a sentence is not in itself a finding about the gene and the disease.
cancer (continued). "Several DUBs, including USP10, USP18, USP22, USP43, and USP51 have been identified as key regulators of ZEB1 stability, thereby promoting proliferation, migration and invasion of cancer cells across different malignancies." (PMID 39736693, 2024). "We next searched the Cancer Genome Atlas (TCGA) database for altered expression of SLC7A11, KCTD10, and USP18 in human cancer tissues." (PMID 38959043, 2024). "Here we show that depletion of ubiquitin specific protease 18 (USP18), a negative regulator of IFN signaling, selectively induces cancer cell ICD." (PMID 36646704, 2023). "Many well-known proteins that play crucial roles in cancer like IL10, USP18, and IL22 were included in this network." (PMID 37697300, 2023). "Here the authors show that USP18, a negative regulator of IFN signaling protects cancer cells from ICD by suppressing the expression of canonical and non-canonical IFN-stimulated genes." (PMID 36646704, 2023). "In this study, we found that depletion of Usp18 induced ICD and consequently delayed cancer progression in both hematological and solid malignancies." (PMID 36646704, 2023). "We previously reported increased ubiquitin-specific peptidase 18 (USP18) expression in lung and other cancers." (PMID 35387560, 2022). "Previous studies have shown that the absence of USP18 increases ISGylation and, conversely, reduces cancer growth by regulating unstable growth modulators and inducing apoptosis." (PMID 39334957, 2024). "Consequently, both a USP18 inhibitor and a PLK2 kinase inhibitor can induce cancer pyroptosis and hold significant potential as cancer therapeutic agents." (PMID 38799433, 2024). "The survival benefit of Usp18 heterozygous deletion was ablated when IFN signaling was disrupted, confirming the link between USP18, IFN signaling, and anti-cancer phenotypes." (PMID 36646704, 2023). "The scope of the studies includes model experiments, an introduction or a correction of disease-associated mutations, the analysis of the function of individual genes (e.g., USP18 and LRRK2 and the generation of transgenic macrophages and myeloid cell lines for cancer therapy." (PMID 37629049, 2023). "This function allows USP18 to regulate both typical ISGs and non-canonical ISGs that are important for the induction of cancer cell pyroptosis." (PMID 36646704, 2023). "Considering these trends, we wondered whether Usp18 depletion may enhance ICD and delay cancer development." (PMID 36646704, 2023). "Accordingly, depletion of USP18 activates miR–7 and subsequently downregulates the expression of EGFR, thereby leading to the suppression of tumorigenesis and the facilitation of apoptosis of cancer cells." (PMID 32957626, 2020). "Among various deubiquitinases, ubiquitin-specific peptidase 18 (USP18) plays a critical role in orchestrating the regulation of innate immune responses and multiple biological processes, including inflammation, innate antiviral immunity, autophagy, cell development, and cancer cell pyroptosis." (PMID 38779488, 2024). "Consequently, the suppression of USP18 not only enhances the expression of canonical IFN-stimulated genes (ISGs) but also activates a set of atypical ISGs and NF-κB target genes that induce cancer pyroptosis." (PMID 38799433, 2024). "USP18, an IFN-stimulated gene 15 (ISG15) DUB, which contains α-helical thumb domain at the N-terminus, the C-terminal palm domain, and the finger domain, has been reported to occupy essential position in various physiological and pathophysiological processes, especially in cancers." (PMID 36582601, 2022). "For instance, the resistance of cancer stem cells to IFN treatments may be attributed partially to the fact that they spend the majority of time in G0/G1, resulting in high USP18 expression and low IFN responsiveness." (PMID 32945770, 2020).
cancer (continued). "Consequently, USP18 suppression not only enhances expression of canonical IFN-stimulated genes (ISGs), but also activates the expression of a set of atypical ISGs and NF-κB target genes, including genes such as Polo like kinase 2 (PLK2), that induce cancer pyroptosis." (PMID 36646704, 2023). "Therefore, targeting USP18 may expand the use of type I IFN treatment to previously unresponsive cancer subtypes, by switching from non-immunogenic to ICD." (PMID 36646704, 2023). "Yet, a direct role for USP18 in transcription regulation has not been reported, but it might form a complex with STAT2/STAT1/IRF9 to enhance expression of ISGs in cancer cells." (PMID 37002195, 2023).
bacterial infections (8 papers, 2009 to 2025). "USP18 might play a role in controlling bacterial infections, as suggested in a study using mice with a mutation in USP18 that showed increased bacterial loads, increased inflammatory responses, and increased activity of the type I IFN signaling pathway." (PMID 31886294, 2019). "In bacterial infections, USP18 inhibits NEMO ubiquitination, negatively regulating the TAK1-TAB complex to suppress NF-κB activation." (PMID 38673764, 2024). "SOCS and USP18 proteins have been reported to promote bacterial infection, whereas few IFI44 proteins have been studied." (PMID 36189314, 2022). "Additionally, USP18 dampens antibacterial TNF-α signaling and ROS production, increasing the susceptibility to bacterial infections." (PMID 38673764, 2024). "Second, USP18 can boost the susceptibility of S. aureus by negatively regulating the IFN-I pathway to reduce TNF-α signaling, and inhibition of USP18 can improve the body’s bacterial infection status." (PMID 36189314, 2022). "Accordingly, USP18 has been suggested to be involved in versatile cellular processes, including signal transduction pathways, stress responses and responses to viral and bacterial infections." (PMID 32957626, 2020). "Additionally, Usp18 is remarkably induced after viral or bacterial infection." (PMID 32957626, 2020). "We showed that the median expression of certain genes (IFI27, HLA-DRB1, USP18, STAP1, and OAS3) in the Biomeme HR-B/V classifier was higher in viral versus bacterial infection." (PMID 41496780, 2025). "When comparing gene expression in viral versus bacterial infection, five classifier genes (OAS3, IFI27, USP18, DSC2, RSP21) were significantly differentially expressed." (PMID 41496780, 2025). "The role of USP18 in the control of bacterial infection has not yet been fully clarified." (PMID 32957626, 2020).
brain disease (2 papers, 2019 to 2023). "In mice, Usp18 negatively regulates Stat1 activation and the downstream IFN-I response by interaction with Ifnar2, and mice lacking Usp18 in microglia display brain disease due to uncontrolled IFN-I signalling." (PMID 36753016, 2023).
kidney (2 papers, 2022 to 2024). "In vivo effects of USP18 on metastases were elucidated using two different murine syngeneic lung metastases models, a tail-vein injection model, and a subcutaneous injection model." (PMID 35387560, 2022).
kidney disease (1 paper, 2024). "Nevertheless, this study represents the first comprehensive insight into the role of serum and urine USP18 in the pathophysiology of the entire spectrum of renal disease." (PMID 38791035, 2024). "Additional research is needed to fully understand the role of USP18 in kidney diseases." (PMID 38791035, 2024).
psychiatric disorder (1 paper, 2025). A disorder characterized by behavioral and/or psychological abnormalities, often accompanied by physical symptoms. "The 22q11.21 rCNV associated with “Any psychiatric disorder” in this study duplicates genes plausibly altering brain function: USP18, DGCR6, and PRODH." (PMID 41510264, 2025).
USP18 also shares sentences with these, for which no sentence is quoted: neurological disorders (4 papers); clear cell renal cell carcinoma (2); infectious disease (2); kidney cancer (2); multiple sclerosis (2); myeloproliferative disease (2); tuberculosis (2); vasculopathy (2); adenocarcinoma (1); Alzheimer disease (1); amyotrophic lateral sclerosis (1); bladder urothelial carcinoma (1); blood cancer (1); calcification (1); cat-eye syndrome (1); Cerebral ischemia (1); colorectal adenocarcinoma (1); cryopyrin-associated periodic syndrome (1); cutaneous melanoma (1); depression (1); dilatation (1); endocrine system disorder (1); endometrial carcinoma (1); esophageal cancer (1); familial chilblain lupus (1); Fanconi anemia (1); gastric carcinoma (1); genetic disorder (1); graft versus host disease (1); hairy cell leukemia (1).
A further 30 diseases each share a sentence with USP18 in 1 paper.